HIF1A (hypoxia inducible factor 1 subunit alpha)
Diseases named in the same sentence as HIF1A in open-access papers (continued):
Sharing a sentence is not in itself a finding about the gene and the disease.
tumor (continued). "Such an effect of the combined treatment is due to a double consequence on tumor cells, first through an impact on tumor vascularization with hypoxia, increase of HIF-1α protein expression and intracellular acidosis, and, second, decrease of CAIX protein which is not available to correct acidosis." (PMID 33889306, 2021). "The radioresistance of hypoxic tumor cells may also depend on the antisense transcript of HIF-1a (AHIF) expression." (PMID 33806538, 2021). "Then, the in vitro effects of OR7E156P upon the invasion and proliferation, and HUVEC (human umbilical vein endothelial cell) tube formation ability were examined under normoxia or hypoxia, and the dynamic effects of OR7E156P and HIF1A on tumor growth in nude mice in vivo were examined." (PMID 34422645, 2021). "Moreover, miR-21 present in TEX promoted tumor growth by increasing the permeability of blood vessels and the accumulation of hypoxia-induced factor-1α (HIF-1α) under both normoxic and hypoxic conditions." (PMID 33803617, 2021). "The HIF-1α/LDHA pathway is involved in tumor-protective responses against radiotherapy." (PMID 33664256, 2021). "Hypoxia, the low oxygen concentration in the tumor microenvironment, can influence the tumor cells, infiltrating blood cells and CAFs to alter the secreted cytokines and growth factors in a HIF-1α-dependent manner, which results in the acquisition of CSC properties." (PMID 33968778, 2021). "However, we were unable to clearly define hypoxic regions of the tumor, due to the genetic or chemical inhibition of HIF1α, which we normally use to define hypoxia." (PMID 34820369, 2021). "Additionally the U251 tumor is more invasive and infiltrative than U8753, and U251 cells display greater necrosis, expression of hypoxia-inducible factor 1-alpha (HIF1α) and of Ki67, indicating higher rates of proliferation." (PMID 33758290, 2021). "Yet another previous study revealed that YY1 could stabilize hypoxia-inducible factor-1 alpha (HIF1α) to increase HIF1α expression, thus promoting tumor growth." (PMID 33722608, 2021). "Interestingly, the HIF-1α-promoted aerobic glycolysis in turn stabilizes HIF-1α, forming a feed-forward loop that promotes tumor growth." (PMID 33796526, 2021). "These contradictory results indicate that there might be a balance of HIF-1α activity and the function of cytotoxic T cells in the tumor microenvironment and highlight that these issues are ripe for additional investigation." (PMID 34202979, 2021). "Wang’s study shows that silencing of IDH2 in prostate cancer cells increases glucose consumption and lactate production as well as the production of ROS and leads to the expression of the HIF1a pathway with increased tumor cell invasion but reduces the tumor cell proliferation and tumor volume." (PMID 34948229, 2021). "Also, cancer biopsies from patients indicated that HIF-1α is overexpressed in several tumours and showed that its level of expression correlated with prognosis and mortality." (PMID 34154667, 2021). "In addition, macrophages from hypoxic tumor areas activate HIF-1α, which mediates the expression of inhibitory receptors of T-cell regulation and thus sponsors the dysfunction of tumor-specific T cells." (PMID 34207035, 2021). "In our study, we show that the targeting of the transcription factor HIF-1α or its regulatory pathways disrupts the mutual interactions occurring between the tumor microenvironment and CLL cells and exerts anti-tumor effects, by acting both at the leukemic cell- and stromal cell-level." (PMID 34207596, 2021). "In line with this hypothesis, generated on the basis of our in vitro data, HIF-1α regulatory pathways can be simultaneously targeted in the stromal and neoplastic compartment with the aim of disrupting their pro-tumor cooperation." (PMID 34207596, 2021). "Thus, Hif1a deletion in the primary tumor reduces bone dissemination but also specifically promotes lung metastasis." (PMID 34556788, 2021).
tumor (continued). "These androgen-specific mechanisms may interact with previously defined effects of NO on hypoxia-induced HIF-1a and tumor angiogenesis, compounding the effect of nitric oxide on prostate cancer." (PMID 33513777, 2021). "Furthermore, GSK-3β promotes tumor cell apoptosis by inhibiting HIF-1α and facilitating apoptotic transcription factors." (PMID 33805447, 2021). "Further studies confirmed higher tumor expression and plasma levels of IL-8, TGF-β1, and TGF-β3, as well as showed other factors’ increases (e.g., epidermal growth factor (EGF), GM-CSF, IFN-α, TGF-β2, and HIF-1α) in the tumor and serum of CRC cachectic patients." (PMID 33557173, 2021). "We have found that biglycan increased HIF1-α and Glut1 expression in tumor cells." (PMID 33966638, 2021). "The metabolic landscape is also, in a large part, determined by the hypoxia-inducible factor 1-alpha (HIF-1α) in the hypoxic tumour environment, MYC, and other signalling pathways, including the phosphatidylinositol 3-kinase (PI3K)–AKT, NOTCH, and the mammalian target of rapamycin (mTOR)." (PMID 34968247, 2021). "Vasculogenic mimicry is often observed in the hypoxic tumor microenvironment and is characterized by an increase in HIF-1α/MMP-9/VEGF signaling, the activation of epithelial-mesenchymal transition (EMT)-related proteins such as Twist1, and an upregulation of proinflammatory molecules such as IL-6." (PMID 34359588, 2021). "Tumor cells initiate hypoxia-induced mechanisms to fuel cell proliferation, invasion, and metastasis, largely mediated by low O2-responsive Hypoxia-Inducible Factor 1 Alpha (HIF-1α)." (PMID 34367973, 2021). "Instead, HIF1α deficient NK cells increased the concentration of an angiogenic cytokine, vascular endothelial growth factor (VEGF) and disabled productive angiogenesis required for tumour progression." (PMID 34090499, 2021). "Importantly, HIF-1α inhibition altered tumor metabolism in mice exposed to a low oxygen environment (7% O2 for 3 h), enhancing RT response but having minimal effect on tumors in air-breathing animals." (PMID 34900673, 2021). "Interestingly, using an autochthonous ccRCC mouse model, a recent study demonstrated that HIF1α is essential for tumor formation whereas HIF2α deletion has only minor effects on tumor initiation and growth in mouse model." (PMID 34384473, 2021). "Interestingly, the total tumor weight was greater on average in Hif1α−/− PyMT+ mice upon sacrifice, while the number of tumors per mouse was not significantly increased." (PMID 34556788, 2021). "HIF1A is a key oxygen-regulated transcriptional activator, playing a fundamental role in the adaptation of tumor cells to hypoxia by up-regulating the transcription of target genes related to multiple biological processes, including cell survival, proliferation, angiogenesis and anti-apoptosis." (PMID 34132347, 2021). "Interestingly, O. japonica was shown to lower the number of migrating and invading cells in a hypoxic tumor microenvironment, accelerating tumor growth and metastasis by suppressing hypoxia-inducible factor (HIF)-1α signaling." (PMID 33567572, 2021). "Deletion of HIF1α R282 methylation significantly inhibits tumor progression and angiogenesis." (PMID 34753906, 2021). "Although the abundant vascular system is the key to energy supply and growth of tumour cells, the abnormal vascular structure may cause poor blood flow and elevated blood pressure, leading to hypoxic TME and production of HIF‐1α." (PMID 34120414, 2021). "Besides, since the tumor progression requires angiogenesis in the stroma, we compared the angiogenesis between stroma-low and stroma-high subgroups with the HIF-1α expression of tumor cells and MVD of the stroma." (PMID 33810015, 2021).
tumor (continued). "Another potential survival pathway regulated by HIF1α in tumor cells is through the increased expression of BCL2/adenovirus E1B 19 kDa protein-interacting protein 3 (BNIP3), a component of autophagosomes that complexes with p62 LC3 complex proteins to initiate a survival mechanism of self-renewal." (PMID 34396954, 2021). "An overall lack of hypoxia-inducible factor (HIF)-2α expression has been found in an analysis focusing on the expression of HIF-1α and HIF-2α proteins in SCLC; however, strong expression of HIF-1α has been observed in most cases, particularly adjacent to necrotic tumor regions." (PMID 34958428, 2021). "HIF-1α is one of the factors secreted by tumor cells, which help to the tumor cell expansion." (PMID 33417986, 2021). "Taken together, it appears that hypoxia upregulates tumor dissemination in general at the transcriptomic level, suggesting that the increase in lung tumor burden may be due to altered Hif1α−/− tumor cell response to signals from the lung microenvironment." (PMID 34556788, 2021). "It has been demonstrated that tumor-derived lactate is a potent inducer of HIF-1α in TAM." (PMID 34389031, 2021). "Moreover, HIF-1α can trigger more than 60 genes involved in tumor growth, metastasis, cellular metabolism, the reduction of apoptosis, and poor prognosis." (PMID 34680470, 2021). "HIF-1α is well known as one of the major regulators of the hypoxic response and controls hypoxic expression of erythropoietin, as well as the expression of genes with metabolic functions, which is essential in tumor genesis and inflammation." (PMID 34917160, 2021). "Various hypotheses were successively raised, including angiogenic escape, revascularization, tumor hypoxia-driven upregulation of HIF1A, and alternative proteins or pathways." (PMID 34306023, 2021). "Moreover, we elucidate that MAP17-induced ROS activate AKT and increase HIF1α protein stability to promote the Warburg effect and tumor growth." (PMID 33832535, 2021). "In addition, the bis-RNAi/EVs system exhibited more obvious tumour suppression than the HIF-1α/EVs system, indicating the enhanced therapeutic performance of our multiantenna gene regulation system." (PMID 34172725, 2021). "Finally, we concluded that our in silico TGEM (conceptually defined by the permanent activation and inactivation of NFκB and HIF1-α, respectively) induced phenotypes against cancer cells in the tumor microenvironment." (PMID 34177892, 2021). "At the tumor margin, blood vessels grow to provide sufficient nutrients and oxygen, allowing the synthesis and rapid ubiquitin-mediated degradation within 10 min of HIF-1α under normoxia." (PMID 34465721, 2021). "In a number of human and murine MC HIF1α was shown to be upregulated when cells mature or locate near a tumor and in meningeomas HIF1α immunoreactivity correlates with occurrence of tryptase+ MC suggesting a role for MC in the HIF1α mediated defense against tumor growth." (PMID 33815383, 2021). "The extent of tumor invasiveness and metastasis, after anti-angiogenic therapies depends on the coordinated interaction of numerous proteins and enzymes controlled by several transcription factors such as HIF-1α and AP-132–34." (PMID 34764332, 2021). "Furthermore, HIF-1α was recently reported to upregulate the expression of PD-L1 in tumor-infiltrating macrophages, thereby promoting the establishment of an immunosuppressive TME." (PMID 34603327, 2021). "Furthermore, it was reported that STAT3 can work as a tumor suppressor by inhibiting aerobic glycolysis of tumor cells, which decreases glucose consumption, lactate production, and expression of HIF-1α target genes in the tumor cells." (PMID 34692527, 2021). "Unfortunately, bortezomib was ineffective in controlling metastatic CRC disease, but a significant accumulation of HIF-1α was seen in tumor specimens and xenograft models, suggesting that proteasome inhibition could alter the response to tumor hypoxia." (PMID 34680186, 2021).
tumor (continued). "Also, R-2-HG can inhibit the activity of prolyl hydroxylase (PHD), which is an α-KG dependent dioxygenase focusing on the degradation of hypoxia-inducible factor 1α (HIF-1α), finally facilitate oncogenesis and tumor progression." (PMID 34425876, 2021). "Numerous related reports also show that the overexpression of HIF-1α could induce the overexpression of PD-L1 in tumor tissues." (PMID 33933077, 2021). "We next investigated whether HIF-1α also played a role in controlling the tumor supportive functions of the SC compartment." (PMID 34207596, 2021). "Nitric oxide, being generated by tumor-associated macrophages in response to irradiation, modifies cysteine 533 in the ODDD of HIF-1α, which preserves its molecule from oxygen-dependent degradation and, thus, ensures the functional activity of HIF-1α under normoxia." (PMID 33806538, 2021). "Another study in a mouse model and clinical samples established that HIF-1α is a potent inhibitor of nuclear factor kappa B (NF-κB) signaling driven by interleukin (IL)-18 and the antitumor activity of tumor-infiltrating NK cells and, therefore, represents a potential immunotherapy target." (PMID 34489925, 2021). "HIF-1a is an important regulatory factor of tumor angiogenesis." (PMID 34815366, 2021). "A high HIF-1α expression has also been considered as a contributor to radioresistance via increasing the ability of DNA repair, inhibiting apoptosis, and mediating the reprograming of energy metabolism in tumor cells." (PMID 34249682, 2021). "Therefore, HIF-1α is considered as a tumor suppressor whereas HIF-2α is considered as an oncogene in ccRCC." (PMID 33547392, 2021). "Indeed, targeting HIF-1α in a melanoma mouse model resulted in increased cytotoxic NK and T cell infiltration in the tumor, which showed increments in CCL2 and CCL5 chemokines." (PMID 34696251, 2021). "Additionally, the effect of MCT1 downregulation on tumour hypoxia markers was characterized by an assessment of expression of the HIF-1α downstream target CAIX." (PMID 34298681, 2021). "Activation of STAT3 stimulates tumour-associated angiogenesis via modulating the stability and activity of hypoxia-inducible factor-1α (HIF-1α) as well as enhancing VEGF expression by binding to the VEGF promoter with HIF-1α." (PMID 34298667, 2021). "HIF1α may elicit protective mechanisms that not only defend tumor cells against PDT, but may further drive tumor progression by sustaining angiogenesis and EMT." (PMID 34371724, 2021). "For this reason, tumor cells harboring an amplification of STIM1 may be able to thrive under hypoxic conditions by activating HIF1a through SOCE, circumventing the dampened ER stress response and ATF4-dependent HIF1a activation." (PMID 33919156, 2021). "The obtained H-MnO2-PEG/TP nanoshells decomposed in the acidic TME, releasing the loaded drugs (TP) and simultaneously attenuated tumor hypoxia and hypoxia-inducible factor-1α (HIF-1α) expression by inducing endogenous tumor hydrogen peroxide (H2O2) decomposition." (PMID 34039370, 2021). "CDK1 has been shown to promote tumor angiogenesis by stabilizing HIF-1α, and its disruption could inhibit retinal angiogenesis by inducing cell cycle arrest and apoptosis." (PMID 33393628, 2021). "Further, HIF-1α activates the transcription of genes encoding transferrin, VEGF, endothelin-1, and inducible nitric oxide synthase (NOS2), which are implicated in vasodilation, neovascularization, and tumor metastasis." (PMID 34178680, 2021). "Finally, this potential tumor-suppressive role of HIF1A in normoxic cancer cells suggests caution in applying therapeutic approaches aiming to inhibit HIF1A signaling." (PMID 33654095, 2021).
tumor (continued). "Moreover, the R2* values of BOLD-MRI showed a positive correlation with HIF-1α, indicating that the R2* values are a promising parameter to predict tumor hypoxia." (PMID 33996599, 2021). "Studies have shown that HIF‐1α expression is related to tumour invasion depth." (PMID 33439514, 2021). "On the other hand, hypoxia induced release of chemoattractants (such as HIF-1α and HIF-2α) and tumor derived cytokines (such as IL-10, IL-4, and TGF-β) are able to hijack tumor-associated macrophages (TAMs) and tumor-associated dendritic cells (TADCs) functions, resulting in tumor metastasis." (PMID 33761933, 2021). "Among these metabolic targets, HIF-1α is an upstream master regulator of tumor metabolism." (PMID 33716751, 2021). "Finally, they describe the downstream effects of HIF1α expression in a hypoxic tumor microenvironment." (PMID 35127517, 2021). "Its expression can be induced by hypoxia, which is a common feature of cancers contributing to tumor metastasis, angiogenesis, expansion of tumor-initiating cell, chemoresistance, and genomic instability via the regulation of hypoxia-inducible factors such as HIF-1α and HIF-2α." (PMID 34354701, 2021). "Whereas the depletion of nutrients and oxygen within the TME comprises T cell function, tumor hypoxia and lactate accumulation drive HIF-1α stabilization in MDSC, thus upregulating PD-L1 expression and promoting a metabolic switch to fatty acid oxidation (FAO)." (PMID 33430105, 2021). "HIF-1α is involved in carcinogenesis, tumor angiogenesis, and cancer progression." (PMID 34740372, 2021). "In addition, recent studies have discovered that HIF-1α is related to poor prognosis in most tumours." (PMID 34256803, 2021). "Interestingly, while tumor progression is delayed, total tumor weight was higher on average in Hif1α−/− PyMT+ mice than in Hif1αf/f PyMT+ mice." (PMID 34556788, 2021). "Since HIF-1α expression is associated with worse outcomes, many chemical compounds and drugs have been tested, showing inhibition of HIF-1α and subsequent processes involved such as tumor growth or metastasis." (PMID 34359734, 2021). "The in vitro and in vivo findings indicated that the co-treatment of CaO2-MNPs and DOX could be an effective approach to diminish HIF1α-mediated hypoxic response to modulate tumor growth of TNBC." (PMID 33546453, 2021). "In addition, we performed histological staining of tumor sections with antibodies against HIF-1α and LC3, the readouts of hypoxia and autophagy, respectively." (PMID 33546453, 2021). "It has been demonstrated that the mitochondrial ROS may stabilize HIF1α, which further promotes cell invasion and vasculogenic tumor mimicry." (PMID 33803640, 2021). "Many tumor tissues show higher expression levels of HIF-1α than normal tissues." (PMID 34360919, 2021). "Furthermore, HIF-1α has been also considered a main factor involved in tumor metastasis by promoting epithelial to mesenchymal transition (EMT) of cancer cells." (PMID 34440169, 2021). "Therefore, mTOR hyperactivity provides stabilization of HIF1α protein and other regulatory failures contributing to the HIF1α stabilization in pseudohypoxic tumor tissues." (PMID 34257622, 2021). "Driven by HIF-1α, drug efflux pumps such as P-glycoprotein (P-gp) are over-expressed, which can not only protect tumor cells by pumping cytotoxic chemotherapeutics to the extracellular spaces but also protect the molecular targets by transporting drugs into the lysosomal lumen from the cytoplasm." (PMID 34277702, 2021). "We hypothesized that the AKT activation by MAEL can be resulted in VEGF activation via the mTOR and HIF1a which probably enhanced the angiogenesis and tumor size in GC patients." (PMID 33902648, 2021). "The reliance of CAFs on aerobic glycolysis may be driven by oxygen availability in the tumor site, HIF-1α stabilization, transforming growth factor-β (TGF-β), or PDGF signaling." (PMID 33514004, 2021).